CD14 (CD14 molecule)
Diseases named in the same sentence as CD14 in open-access papers (continued):
Sharing a sentence is not in itself a finding about the gene and the disease.
pneumococcal meningitis (2 papers, 2006 to 2007). An acute purulent infection of the meninges and subarachnoid space caused by Streptococcus pneumoniae, most prevalent in children and adults over the age of 60. "In pneumococcal meningitis, we found a shorter survival in CD14-/- than in wt mice, which was due to enhanced CXCR2 expression leading to early recruitment of leukocyte and increased TNF in cerebrospinal fluid (CSF)." (PMID 17428319, 2007). "In a murine model of pneumococcal meningitis increased CSF concentrations of sCD14 correlates with CD14 transcriptional upregulation mainly in intrathecal leukocytes." (PMID 16749930, 2006). "In the infant rat model of pneumococcal meningitis, the two distinct expression kinetics of CD14 observed in the CX and in the HC suggest that parenchymal cells, most likely astrocytes and microglia, also contribute to the inflammatory cascade by increasing CD14 expression." (PMID 16749930, 2006). "This study has compared outcome and treatment effects of antibiotics and TACE inhibitor TNF484 during pneumococcal meningitis in mice lacking the pattern recognition receptors TLR2 and/or CD14." (PMID 17428319, 2007).
polymyositis (2 papers, 2015 to 2024). A rare idiopathic inflammatory myopathy characterized by symmetric proximal muscle weakness and elevated muscle enzymes. "Our results conflict with those of authors who report detection by direct flow cytometry of CD105, CD90, and CXCR4 on MPs from mesenchymal stem cells and CD3, CD14 and CD19 on MPs from the plasma of polymyositis/dermatomyositis patients." (PMID 25978814, 2015).
postmenopausal osteoporosis (2 papers, 2022 to 2023). Metabolic disorder associated with fractures of the femoral neck, vertebrae, and distal forearm. "MiR-218 is also found to be downregulated in CD14+ peripheral blood mononuclear cells from patients with postmenopausal osteoporosis, further emphasizing its role in bone metabolism." (PMID 37596575, 2023). "Here, we aimed to show how CD14+ monocytes contribute to the pathophysiology of coexisting postmenopausal osteoporosis and carotid atherosclerosis." (PMID 35937796, 2022).
primary myelofibrosis (2 papers, 2016 to 2019). Myelofibrosis with myeloid metaplasia is a myeloproliferative disease with annual incidence of approximately 1 case per 100,000 individuals and age at diagnosis around 60 (an increased prevalence is noted in Ashkenazi Jews). "Evaluation of CD14+ cell and cell subsets in spleen derived MNCs of patients with primary myelofibrosis (PMF) and of healthy subjects (CTRLs)." (PMID 27281335, 2016). "To confirm that neoplastic monocyte-derived collagen- and fibronectin-producing fibrocytes induce bone marrow (BM) fibrosis in primary myelofibrosis (PMF), we injected PMF BM-derived fibrocyte-precursor CD14+/CD34- monocytes into the tail vein of NOD-SCID-γ (NSG) mice." (PMID 31569199, 2019).
pulmonary sarcoidosis (2 papers, 2020 to 2024). Sarcoidosis affecting the lung parenchyma. "According to flow cytometry data, the proportion of CD14++CD16 macrophages from BALF in the subgroup of patients with pulmonary sarcoidosis was lower than in that in healthy people, and the proportion of CD14++CD16+ in the subgroup was higher." (PMID 39795474, 2024). "Our results show differences in TREM-1 and TREM-2 expression on CD14+ cells in bronchoalveolar lavage between pulmonary sarcoidosis and HP." (PMID 32508528, 2020). "In pulmonary sarcoidosis, we noticed a decrease in TREM-1+CD14+ cells, CD4+ T cells, DLCO and increase in CD8+ T cells in relationship with HRCT images acquired from the most benign to the most severe type." (PMID 32508528, 2020).
rectal cancer (2 papers, 2022 to 2024). A primary or metastatic malignant neoplasm that affects the rectum. "In patients with rectal cancer, who had the percentage of CD14+CD16+CCR2+ monocytes below 20% out of CD14+CD16+, the percentage of CD14+CD16+CCR2+ was increased after NAC (in 6 out of 7 patients tested)." (PMID 36733385, 2022). "In rectal cancer, correlation of PFKFB3 expression with CD14, but not with M2-like markers was found." (PMID 36733385, 2022). "Both NAC and surgical intervention affected proportion of CCR2+ and CD163+ monocytes within non-classical CD14-CD16+ and CD14+CD16+ subsets in patients with CRC, and effects were specific for colon and rectal cancer patients." (PMID 36733385, 2022).
renal carcinoma (2 papers, 2013 to 2018). A carcinoma arising from the epithelium of the renal parenchyma or the renal pelvis. "Patients with renal cancer have immunosuppressive CD14−CD15+CD11b+CD66b+ granulocytic MDSCs 20], whereas CD14+HLA-DR−/low monocytic MDSCs circulate in the blood of patients with melanoma, multiple myeloma, prostate cancer, hepatocellular carcinoma or head and neck cancer 21–24]." (PMID 23437326, 2013).
renal dysfunction (2 papers, 2020 to 2022). "Both Cystatin C and CD14 were associated with increased risk of renal dysfunction in all three EV sub‐fractions." (PMID 32648717, 2020). "A cohort study showed that a level of pro-inflammatory Cd14 was elevated in patients with renal dysfunction; this may be because of the increased inflammatory status that contributed to the development of kidney dysfunction." (PMID 35308536, 2022). "Cystatin C in plasma was also associated with increased risk of renal dysfunction (OR of 2.89), whereas CD14 in plasma was not." (PMID 32648717, 2020). "Given the relevance of renal dysfunction, inflammation, and the coagulation system in the development of cardiovascular diseases, we extended previous work on Cystatin C, CD14, SerpinG1, and SerpinF2 within circulating EVs to explore their possible associations with the CRS." (PMID 32648717, 2020).
renal fibrosis (2 papers, 2017 to 2022). A final common manifestation of a wide variety of chronic kidney diseases characterized by glomerulosclerosis and tubulointerstitial fibrosis. "Preterm infants showed increased urine CD14, and high urine CD14 was a risk factor of renal fibrosis among patients with acute rejection after kidney transplantation." (PMID 28522940, 2017). "Consistently, our results showed that the levels of F4/80 and CD14 were markedly increased in the kidneys of diabetic mice by immunohistochemical staining, indicating that the kidneys of our model were exposed to the persistent induction of worsened renal fibrosis." (PMID 36448056, 2022).
retinal degeneration (2 papers, 2015 to 2017). Degeneration of the retina. "Our results using a CD14-blocking antibody and a recent report that subretinal MP accumulation is TLR4 dependent in a retinal degeneration model back the notion that TLR signaling is involved in the alteration of the immunosuppressive environment." (PMID 25604058, 2015). "The expression of macrophage markers (CD14 and MAC-1), neutrophils (Ly6G), monocyte chemoattractant protein (MCP-1), angiogenesis marker (VEGF) and matrix metalloproteases (MMP-1 and MMP-2) were also upregulated in retinal degeneration models CBA/J and NOD.SCID-rd1." (PMID 28258056, 2017).
RSV bronchiolitis (2 papers, 2016 to 2022). "We report an association of recurrent RSV bronchiolitis with a loss of CD14 function in immune cells." (PMID 35429403, 2022). "We describe the first child with a homozygous frameshift mutation in CD14, leading to autosomal recessive CD14 deficiency, as a novel genetic etiology associated with recurrent RSV bronchiolitis." (PMID 35429403, 2022). "Autosomal recessive CD14 deficiency is a novel genetic etiology associated with recurrent RSV bronchiolitis." (PMID 35429403, 2022). "After a careful check of their abstracts and/or full‐text reviews, 20 articles were excluded unrelated to TLR4 Asp299Gly (rs4986790), TLR4 Thr399Ile (rs4986791), CD14 C‐159T (rs2569190) polymorphisms and RSV bronchiolitis." (PMID 26901241, 2016). "However, it is worth to note that different types of CD14 C‐159T polymorphism could play varied roles in developing RSV bronchiolitis." (PMID 26901241, 2016). "Although single-nucleotide polymorphisms (SNPs) in the CD14 and TLR4 genes have been associated with severe RSV bronchiolitis, a genetic link to recurrent or severe disease has not been described." (PMID 35429403, 2022).
schwannoma (2 papers, 2024 to 2025). A benign, usually encapsulated slow growing tumor composed of Schwann cells. "In this study, we found that sEVs secreted by NF2-associated schwannomas (NF2-EVs) facilitate the conversion of CD14+ monocytes into an MDSC-like phenotype, showcasing MDSC-like inhibitory functions." (PMID 41149489, 2025).
small cell lung carcinoma (2 papers, 2020). Small cell lung cancer (SCLC) is a highly aggressive malignant neoplasm, accounting for 10-15% of lung cancer cases, characterized byrapid growth, and early metastasis. "Subsequently, for small cell lung cancer (SCLC) patients, the frequency of CD14+HLA-DR−/low MDSCs was also found to be negatively correlated with clinical outcomes." (PMID 32005273, 2020).
spondyloarthritis (2 papers, 2017 to 2019). "We used single-cell RNA sequencing of paired blood and synovial fluid from a further three individuals with spondyloarthritis to investigate the CD14 myeloid compartment." (PMID 31594933, 2019).
Takotsubo Syndrome (2 papers, 2022). "Additionally, serum interleukin-6 and chemokine (C-X-C motif) ligand 1 concentrations as well as classic CD14++CD16 monocytes are increased, whereas intermediate CD14++CD16+ and non-classic monocytes are reduced in patients with takotsubo syndrome." (PMID 35344411, 2022). "Furthermore, it has been observed that serum interleukin-6 and chemokine (C-X-C motif) ligand 1 concentrations, as well as classic CD14+ CD16 monocytes, are elevated in patients with Takotsubo Syndrome, but intermediate CD14+ CD16+ and non-classic monocytes are decreased." (PMID 36614928, 2022).
toxoplasmosis (2 papers, 2014 to 2019). A parasitic disease contracted by the ingestion or fetal transmission of toxoplasma gondii. "Whereas, these changes occurred irrespective of a chronic T. gondii infection of the blood donors, we also unraveled distinct differences in the in vitro reactivity of monocytes from chronically infected toxoplasmosis patients and T. gondii naïve individuals with respect to CD14 and HLA-DR,DP,DQ." (PMID 31316920, 2019).
triple-negative breast carcinoma (2 papers, 2024 to 2025). An invasive breast carcinoma which is negative for expression of estrogen receptor (ER), progesterone receptor (PR), and human epidermal growth factor receptor 2 (HER2). "Multiplex immunofluorescence (m-IF) analysis of human triple-negative breast cancer (TNBC) tissues demonstrated co-localization of MARCO with CD11b+ CD14+ cells that were negative for CD68 expression, suggesting potential expression of MARCO on M-MDSCs." (PMID 40695812, 2025).
uremia (2 papers, 2024 to 2025). A clinical syndrome associated with the retention of renal waste products or uremic toxins in the blood. "As uremia has been shown to impair systemic immune cell function, including monocytes, we examined the relationship between serum creatinine and the number of infected CD14+ monocytes in the skin." (PMID 39514579, 2024).
vitamin D deficiency (2 papers, 2017 to 2018). A nutritional condition produced by a deficiency of VITAMIN D in the diet, insufficient production of vitamin D in the skin, inadequate absorption of vitamin D from the diet, or abnormal conversion of vitamin D to its bioactive metabolites. "Of note, serum levels of C-reactive protein, IL-6 and soluble CD14 were significantly higher in patients with versus without severe vitamin D deficiency, and serum levels of soluble CD14 levels declined in patients with de novo supplementation of vitamin D (median 2.15 vs. 1.87 ng/mL, P = 0.002)." (PMID 30408125, 2018). "Among patients with vitamin D deficiency, we also found higher percentages of patrolling monocytes (CD14dimCD16+), which typically express high levels of CX3CR1, and lower percentages of the classical monocyte subset (CD14++CD16-) that typically express CCR2 overall." (PMID 28464004, 2017). "Baseline serum levels of IL-6 and soluble CD14, but not of I-FABP, were significantly higher in patients with severe vitamin D deficiency at baseline compared to patients without severe vitamin D deficiency." (PMID 30408125, 2018).
Abdominal obesity (1 paper, 2015). Excessive fat around the stomach and abdomen. "The exercise group's abdominal obesity was mitigated due to visceral fat reduction; grip strength, push-ups, and oxygen uptake per weight improved; and HDL-C and IgA level also increased, while TNF-α, CD14, and endotoxin levels decreased." (PMID 26075288, 2015).
abortion (1 paper, 2024). the ending of pregnancy by removing a fetus or embryo before it can survive outside the uterus. "In the Monocyte group, the following immunophenotypes all have negative causal relationships with abortion: Monocyte AC and CCR2 on CD14+ CD16+ monocyte were negatively associated with abortion (OR < 1)." (PMID 39388432, 2024).
abscess (1 paper, 2024). An inflammatory process characterized by the accumulation of pus within a newly formed tissue cavity which is the result of a bacterial, fungal, or parasitic infection or the presence of a foreign body. "There was also a tendency for increased MFI in CD14-stained cells of non-abscessed steers compared to abscessed steers on day 56 (abscess P = 0.09)." (PMID 38764468, 2024).
acute leukemia (1 paper, 2024). A clonal (malignant) hematopoietic disorder with an acute onset, affecting the bone marrow and the peripheral blood. "We merged DHSs from CD14+ monocytes, NB4 acute leukemia cells, and HL60 acute leukemia cells, keeping only sites that did not overlap an annotated gene and were present in at least two of the datasets." (PMID 38126767, 2024).
acute-on-chronic liver failure (1 paper, 2018). Acute-on-chronic liver failure (ACLF) is an extreme condition during the natural history of chronic HBV infection, with a relatively high short-term mortality. "In patients with acute-on-chronic liver failure, human CD14+CD15−HLA-DR− MDSCs impair antimicrobial responses." (PMID 30046600, 2018).
adenovirus infection (1 paper, 2019). "Interestingly, we observed for the first time that incubation with recombinant IL-4 can increase adenovirus infection through upregulating the expression of SR-A and integrin receptor on CD14+ monocytes." (PMID 30781810, 2019). "Interestingly, we found that the efficacy of adenovirus infection into CD14+ monocytes was significantly decreased after removing CD3+ T lymphocytes from PBMC samples of Ad-seropositive individuals (preexisting virus-specific CD3+ T cells)." (PMID 30781810, 2019). "However, it is not clear whether T lymphocytes and/or B lymphocytes indirectly affect the efficacy of adenovirus infection into CD14+ cells." (PMID 30781810, 2019).
allergic contact dermatitis (1 paper, 2025). An inflammatory skin condition caused by an immune response to direct contact between the skin and an allergen. "Increased PAR2 expression was observed in the CD11b+/CD14+ myeloid cells in human allergic contact dermatitis." (PMID 39996720, 2025).
aortic stenosis (1 paper, 2017). Aortic valve stenosis is a aortic valve disease caused by the incomplete opening of the aortic valve. "Taking a closer look at the different entities of aortic stenosis, the decline of intermediate CD14++CD16+ monocytes was significant in patients with classical as well as with paradoxical low-flow/low-gradient AS and showed a prominent, albeit insignificant trend in low-flow/flow-gradient AS." (PMID 28829829, 2017).
aortic valve stenosis (1 paper, 2024). Aortic valve stenosis (AVS) is a condition characterized by narrowing of the heart's aortic valve opening. "Similarly, an increased number of CD14++CD16− monocytes has been reported in patients with severe aortic valve stenosis, another model of concentric ventricular hypertrophy due to pressure overload." (PMID 39273110, 2024).
aphthous ulcers (1 paper, 2025). "Increased levels of transcripts for monocyte‐specific genes (e.g. CD14, NOD2, S100A8/A9; Clusters 8 and 14) indicate specific infiltration of these cells into the aphthous ulcers." (PMID 40386941, 2025).
Arrhythmia (1 paper, 2019). Any cardiac rhythm other than the normal sinus rhythm. "Our flow cytometry results showed that the percentage of CD14++CD16- pro-inflammatory monocytes is significantly higher in patients with post-MI arrhythmias than healthy controls and MI patients without arrhythmias (p<0.001)." (PMID 31588225, 2019). "The percentage of CD14++CD16- cells is significantly higher in patients with post-MI arrhythmias (81.84 ± 0.97%) than MI patients without arrhythmias (70.18 ± 1.88%, p=0.047) and controls (61.76± 5.00%, p<0.001)." (PMID 31588225, 2019). "Compared with controls, percentage of CD14+CD16+ monocyte was lower in patients with post-MI arrhythmias (p=0.001) and in MI patients without arrhythmias (p=0.041)." (PMID 31588225, 2019). "Percentages of CD14++CD16+ monocyte subset tended to be higher in patients with post-MI arrhythmias than those without post-MI arrhythmias (8.31 ± 1.04% vs 6.31 ± 1.38%, p=0.782)." (PMID 31588225, 2019).
autoimmune encephalitis (1 paper, 2022). Inflammation of the brain secondary to an immune response triggered by the body itself. "Pathology testing of the postoperative tumour of patient 2 with a large CD14+ monocyte reduction revealed that the tumour was a teratoma, which can cause autoimmune encephalitis." (PMID 35061932, 2022).
basal cell carcinoma (1 paper, 2022). A carcinoma involving the basal cells. "Genes in the low-expression cohorts of CD14, CYBB, NOD2, and TLR1 were all highly enriched in olfactory transduction, linoleic acid metabolism, and basal cell carcinoma." (PMID 36193326, 2022).
Behcet's syndrome (1 paper, 2025). "• The CD14 promoter gene C-159T single-nucleotide polymorphism increases the susceptibility to Behcet's syndrome." (PMID 41186884, 2025).
benign neurofibroma (1 paper, 2021). "Interestingly, expression of CD14 correlated strongly with the expression of BTK in benign neurofibroma (Miller, N = 86) as well as in different NB cohorts except for Hiyama." (PMID 33669187, 2021).
benign prostatic hyperplasia (1 paper, 2017). A non-cancerous nodular enlargement of the prostate gland. "Especially relevant is the identification of CD14 as urine marker to discriminate between benign prostatic hyperplasia (BPH) and PCa with high sensitivity and specificity." (PMID 29164064, 2017).
bone cancer (1 paper, 2010). A primary or metastatic malignant neoplasm affecting the bone or articular cartilage. "A two- to three-fold increase in the mRNA expression levels of microglial activation markers CD11b and CD14 was observed in bone cancer pain rats at days 6 and 12 after inoculation (n = 4, ANOVA1w, P < 0.01, post hoc Dunnett testing)." (PMID 20089147, 2010).
bone marrow disorder (1 paper, 2025). Any disease of the bone marrow. "Six patients had classical PNH with hemolytic anemia and large PNH clones (> 60% neutrophils [FLAER/CD24] and monocytes [FLAER/CD14), three had PNH with small clones (< 10% granulocytes and monocytes) in the context of another bone marrow disorder, and one had subclinical PNH with a clone size < 1%." (PMID 40886199, 2025).
brain inflammation (1 paper, 2022). "Therefore, we isolated CD14+ monocytes from peripheral blood of nine adult male X-ALD patients lacking signs of brain inflammation and nine age and sex-matched healthy controls." (PMID 36528616, 2022).
brain injury (1 paper, 2015). Acute and chronic (see also brain INJURIES, CHRONIC) injuries to the brain, including the cerebral hemispheres, CEREBELLUM, and brain STEM. "In the present study the dynamics of CD14+ monocytes and CD15+ granulocytes in the cerebrospinal fluid of patients suffering from traumatic brain injury were evaluated in the direct posttraumatic course over 72 hours for the first time." (PMID 26568661, 2015).